PRL (prolactin)
Diseases named in the same sentence as PRL in open-access papers (continued):
Sharing a sentence is not in itself a finding about the gene and the disease.
hyperprolactinemia (continued). "Based on the ROC curve, sensitivity/specifity of a PRL threshold of ≥ 60 ng/ml for the diagnosis of microprolactinoma as compared to other causes of hyperprolactinemia in PCOS women, was 100% (95% CI:56.5% -100%) and 93.7% (95% CI:71.7- 99.7%), respectively (AUC = 0.962)." (PMID 35250884, 2022). "Hyperprolactinemia causes symptoms such as galactorrhea and amenorrhea, the former being due to the direct effect of PRL on the mammary glands and the latter due to the suppression of hypothalamic gonadotropin-releasing hormone (GnRH) and pituitary gonadotropin secretion." (PMID 35892862, 2022). "In female patients of schizophrenia, the prolactin-increasing antipsychotics may contribute to menopause and hyperprolactinemia which are associated with decreased bone mineral density and furtherly increase fracture risk." (PMID 35105317, 2022). "The mechanism by which antidepressants may cause hyperprolactinemia is not well understood, though several theories explain the involvement of serotonin stimulation of GABAergic neurons and indirect modulation of prolactin release." (PMID 35339194, 2022). "Hyperprolactinemia, caused by antipsychotics, may be further exacerbated in women as the result of a higher baseline prolactin level compared to that of men." (PMID 36619589, 2022). "Notably, prolactin values should be interpreted with the consideration of current treatments as some medications are known to cause hyperprolactinemia (e.g., psychoactive drugs)." (PMID 33005949, 2021). "These antibodies interfere with PRL measurement and can cause hyperprolactinemia misdiagnosis." (PMID 32949349, 2021). "The cause of hyperprolactinemia in elephants is unknown, making bacterial taxa associated to prolactin ideal for laboratory studies in model species to better understand these relationships." (PMID 34930501, 2021). "During the clinical evaluation of hyperprolactinaemia, disconnection hyperprolactinaemia is generally associated with a serum level of prolactin <2000 mIU/L, although rarely it may be higher." (PMID 34360982, 2021). "Mammosomatotroph adenoma or mixed somatotroph-lactotroph adenoma could directly secret prolactin and cause hyperprolactinemia." (PMID 35154007, 2021). "The dopamine D2 receptor-blocking effect of antipsychotics could elevate the secretion of PRL, causing hyperprolactinemia." (PMID 33987015, 2021). "Bacteria associated to prolactin may be of interest in future studies due to the high incidence of hyperprolactinemia in captive African elephants in North America." (PMID 34930501, 2021). "Non-prolactin secreting PAs can also cause mild hyperprolactinemia via the pituitary stalk effect." (PMID 33946142, 2021). "There was a statistically significant but weak positive association between prolactin and testosterone levels in this cohort of pregnant women which is consistent with the well-known fact that hyperprolactinemia is associated with elevated free testosterone levels in women." (PMID 32908678, 2020). "The absence of changes in glycemia in 12‐ and 18‐month‐old female rats may be related to the high concentration of PRL, as it has been reported that chronic moderate hyperprolactinemia is associated with increased release of insulin induced by a glucose load." (PMID 33075214, 2020). "Some authors suggested that prolactin could be a uremic toxin but until now it cannot be concluded whether hyperprolactinemia is a cardiovascular risk factor or only an intermediate in a major pathophysiological pathway." (PMID 32655635, 2020). "Regarding prolactin, there is a hypothesis thatpolycystic ovaries affect the activity of dopamine in thehypothalamus and cause hyperprolactinemia in thesepatients." (PMID 32112632, 2020). "Median prolactin levels were 93.15 ng/mL, 241.8 ng/mL, 74.5 ng/mL, 93.2 ng/mL, and 69 ng/mL for microadenomas, macroadenomas, idiopathic hyperprolactinemia, drug-induced hyperprolactinemia, and other causes of hyperprolactinemia, respectively." (PMID 30396878, 2019).
hyperprolactinemia (continued). "This is an important finding because treatment with first- and second-generation antipsychotics is often associated with hyperprolactinemia, warranting the need to obtain baseline prolactin measurements and constant monitoring to guide follow-up therapy decisions and shifting strategies." (PMID 31824349, 2019). "PRL plays a critical role in reproductive function; hyperprolactinemia is associated with anovulation and may directly or indirectly cause infertility." (PMID 29622766, 2018). "Despite the evidence on the growing number of antipsychotic users and the potential increased risk of diabetes and hyperprolactinemia in the pediatric population, the incidence proportion of those who received monitoring for glucose and prolactin before and after drug initiation is remarkably low." (PMID 29889543, 2018). "COMMENT 4: Although drug-induced hyperprolactinemia is usually associated with PRL levels < 100 ng/mL, they are largely variable and may overlap those found in patients with prolactinomas." (PMID 29768629, 2018). "Regardless of hypersecretion of prolactin with idiopatic reasons that may lead to hyperprolactinemia due to macroprolactinemia, the most common cause of elevated PRL level (hyperprolactinemia) is prolactin-producing adenomas or prolactinomas." (PMID 28593164, 2017). "In humans and rodents, hyperprolactinemia may negatively affect ovarian function due to elevated prolactin levels, which are associated with the decreased synthesis of sex hormones (estrogen and progesterone) 5-9." (PMID 26375566, 2015). "Further prospective studies may overcome this limitation by repeatedly assessing prolactin levels and cognitive performance over time to explore whether persistent hyperprolactinaemia is a risk factor for cognitive decline in subjects with psychoses." (PMID 24586772, 2014). "Hence, as hyperprolactinaemia is associated with estrogen suppression, the initial prolactin elevation is clinically identified by reproductively related symptoms, primarily in females." (PMID 24490071, 2013). "Anti-PRL autoantibody was found to be one of the major causes of “idiopathic” hyperprolactinemia." (PMID 23304187, 2012). "Moreover, a significant positive correlation was present between anti-PRL autoantibody titers and serum PRL concentrations in humans, suggesting that anti-PRL autoantibody is a cause of hyperprolactinemia." (PMID 23304187, 2012). "The primary aims were to determine the prevalence of SD and hyperprolactinemia in male patients and to investigate whether associations exist between SD and prolactin levels." (PMID 22190916, 2011). "The primary aims of the present study were to determine the prevalence of SD and hyperprolactinemia, and to investigate whether associations exist between SD and prolactin levels in male patients with psychosis." (PMID 22190916, 2011). "Higher doses of prolactin-raising medications are associated with hyperprolactinemia and lower BMD." (PMID 20163720, 2010). "Endogenous GnRH seems to exert a similar effect since treatment of castrated female monkeys with a GnRH antagonist causes PRL plasma concentrations to drop and hyperprolactinemia induced by oestrogen/progesterone treatment is attenuated by administration of a GnRH antagonist." (PMID 18081553, 2008). "Previous studies, that reported normal levels of PRL, have suggested such factors as renal, endocrine and psychiatric disorders, medications and premenopausal situation may be the cause of hyperprolactinemia in patients with colorectal neoplasms." (PMID 15617576, 2004). "Two case reports documented hyperprolactinemia: one associated with mirtazapine, accompanied by galactorrhea, mastodynia, and edema that resolved after drug discontinuation, with another involving bupropion that was attributed to disruption of dopamine-mediated prolactin regulation." (PMID 41426913, 2025).
hyperprolactinemia (continued). "Like tricyclic antidepressants and SSIss, “typical” neuroleptics (phenothiazides) are responsible for hyperprolactinemia, the most common abnormality of the hypothalamic-hypothesis axis, caused by exaggerated production and prolactin (PRL) due to the central dopamine secretion block." (PMID 38397000, 2024). "Hyperprolactinemia is a known cause of insulin resistance in humans, and despite prolactin’s rise during diestrus in dogs as a luteotropic factor, the role of prolactin corroborating insulin resistance induction in dogs is unknown." (PMID 38539988, 2024). "Additionally, PRL facilitates metalloproteinase activity that can degrade extracellular matrices at the feto-maternal interface, which could explain why hyperprolactinemia can cause recurrent miscarriages." (PMID 39205744, 2024). "Moreover, hyperprolactinemia is associated with auto-antibodies that may interfere with the prolactin assay." (PMID 37864188, 2023). "First, correlations between cardiometabolic risk factors and both prolactin and 25-hydroxyvitamin D levels suggest that hyperprolactinemia and low vitamin D status may make women more susceptible to cardiovascular and metabolic complications later in life, despite their young age." (PMID 37242186, 2023). "It was generally believed that the mechanism of hyperprolactinemia-induced sexual dysfunction was caused by a decrease in testosterone secretion, whereas the mechanism could partly be explained by the influence of prolactin on serotonin systems in the brain." (PMID 37886642, 2023). "Notably, antipsychotic-induced hyperprolactinemia is the possible mechanism underlying antipsychotic-induced osteoporosis; however, some of the SGAs, such as olanzapine, quetiapine, and aripeprazole, have a minimal effect on serum prolactin levels." (PMID 37875841, 2023). "In this case, the patient’s hormone levels were within the normal range before treatment; however, after a period of drug treatment, the prolactin level was observed to be significantly higher than normal, which also verified that antipsychotic drugs could cause hyperprolactinemia." (PMID 37867775, 2023). "However, such non-prolactin-producing sellar lesions may mimic prolactinomas due to compression of the pituitary stalk, which decreases the delivery of dopamine, causing hyperprolactinemia due to the missing inhibition effect of dopamine on lactotroph cells." (PMID 36147567, 2022). "This wide spectrum of etiologies presents challenges regarding the diagnosis of hyperprolactinemia; moreover, it might explain why the associations of PRL with some of these conditions are still under investigation, one of them being the link between its levels and PCOS." (PMID 36552931, 2022). "Finally, clinicians must be aware of drug-induced hyperprolactinemia (particularly with antipsychotics and antiemetics) and the presence of macroprolactin, a biologically inactive immune complex between prolactin and IgG which is causative in approximately 10% of cases of hyperprolactinemia." (PMID 36013562, 2022). "In addition to effects on gonadal function, hyperprolactinaemia caused by prolactin secreting tumors of the pituitary gland or the intake of antipsychotic drugs might have effects on food intake, weight gain as well as on glucose and lipid metabolism." (PMID 33902531, 2021). "Some patients also experience hyperprolactinemia due to secondary hyperprolactinemia caused by hypothalamic dopamine transport disorders induced by funnel compression, which was observed in patient 4, who had slightly increased prolactin levels before the operation." (PMID 34210357, 2021). "However, high serum levels of prolactin can also be seen with pregnancy (range: 200–500 μg/L), medication-induced hyperprolactinemia (range: 25–200 μg/L), or the “stalk effect” (range: 25–250 μg/L), where the inhibitory dopamine secretion is blocked and causes a rise in prolactin." (PMID 33946142, 2021).
hyperprolactinemia (continued). "PRL-producing adenomas were also classified through imaging of the pituitary microadenoma and by the presence of serum PRL concentrations between 50 and 200 ng/Ml, because NF macroadenomas may cause mild hyperprolactinemia due to pituitary stalk compression." (PMID 33881731, 2021). "The low plasma progesterone concentrations observed in women with hyperprolactinemia have been attributed to a deficient luteal phase with reduced progesterone secretion that leads to poorly developed endometrium and failure of embryo implantation, so contributing to PRL-induced infertility." (PMID 33162942, 2020). "A particularly challenging scenario is drug-induced hyperprolactinaemia, especially when this occurs in association with antipsychotics or other psychiatric medications, as the degree of PRL elevation can be variable and discontinuing or changing the culprit medication may not be safe." (PMID 31847209, 2019). "Notably, PRL is higher in patients with MS or NMO during attacks compared with phases of remission but it is still unclear whether hyperprolactinaemia is a primary cause or a secondary effect of the disease." (PMID 31847209, 2019). "Moreover, the baseline risk of hyperprolactinemia might be high in Japan due to the fact that prolactin-raising antipsychotics (i.e., risperidone and first-generation antipsychotics) are commonly prescribed to children and adolescents." (PMID 29889543, 2018). "In addition, the ability to regulate PRL levels with selective NR4A2 antagonists may provide novel approaches to manage hyperprolactinemia associated with other autoimmune disorders and conditions." (PMID 25717285, 2015). "Prolactin secreting adenomas or other functional tumours co-secreting prolactin or any form of macroadenoma that is large enough to cause pituitary stalk compression (i.e. disconnection hyperprolactinaemia) may result in hyperprolactinaemia." (PMID 25518745, 2014). "Kidneys clear prolactin, and thus, kidney disease may cause secondary hyperprolactinemia." (PMID 20046401, 2009). "Hyperprolactinemia, defined by at least two elevated prolactin concentrations, occurred in 5,810 individuals (73.9% female), with an incidence of 36.7 per 100.000 person-years." (PMID 41880100, 2026). "Intuitively, HR-QoL improves after prolactin normalization and adenoma shrinkage, because hyperprolactinemia-, hypogonadism-, and mass-related symptoms should recede; however, little is known about HR-QoL after prolactinoma treatment." (PMID 41017446, 2026). "Her history included hyperprolactinemia from a growth hormone- and prolactin-positive pituitary adenoma diagnosed at age 41 and treated surgically, raising the possibility of an endocrine contribution to ductal dilatation and secretory stasis." (PMID 42137657, 2026). "Previous clinical research has shown that CRC patients with hyperprolactinemia, or serum concentration of PRL over 20 ng/mL, had worse prognosis and shorter overall survival compared to patients with healthy PRL serum levels." (PMID 41501898, 2026). "Further screening of serum prolactin levels in 100 patients with retroperitoneal tumours revealed that 90% of the cases exhibited hyperprolactinaemia in our research cohort, encompassing both malignant sarcomas and benign tumours." (PMID 42083506, 2026). "Assessments revealed marked hyperprolactinemia (mean serum prolactin concentration, 3902 ng/mL [SI: 169.8 nmol/L]) (reference range, 5.0-30.0 ng/mL [SI: 0.22-1.30 nmol/L]), and an invasive 47 × 43 × 50 mm adenoma extending into the right temporal lobe." (PMID 42022484, 2026). "We propose to define biochemical recurrence as confirmed serum prolactin elevation (>1xULN) in 2 separate measurements after initial biochemical remission with exclusion of physiological and drug-induced hyperprolactinemia." (PMID 41017446, 2026).
hyperprolactinemia (continued). "Clinicians should consider medication-related hyperprolactinemia in the differential diagnosis when elevated prolactin is detected during GLP-1 receptor agonist therapy." (PMID 42211780, 2026). "Some previous studies classified somatotroph tumors with hyperprolactinemia as GH and PRL cosecreting tumors, whereas other authors considered cosecreting tumors when tumors stained positive for both GH and PRL by IHC." (PMID 40421250, 2025). "The check-up should include the following: weight (BMI), fasting blood glucose, blood lipid levels, prolactin concentration (whenever symptoms of hyperprolactinemia such as breast enlargement, galactorrhea appear), and signs of NMS." (PMID 41303162, 2025). "Thus, our research aims to assess prolactin levels in infertile women of Balochistan, Pakistan, and to establish whether female infertility is associated with elevated prolactin levels and also a possible link between hyperprolactinemia and anemia in infertile women." (PMID 40535391, 2025). "R#15 (conditional): Blood prolactin should be monitored during and after puberty to screen for hyperprolactinemia as comorbidity." (PMID 41215497, 2025). "It appears rational to screen for prolactin levels and hyperprolactinemia‐related comorbidities, especially during/after puberty." (PMID 41215497, 2025). "Hyperprolactinemia (HPRL) is a common clinical condition characterized by elevated levels of prolactin (PRL) production from the pituitary lactotrophs." (PMID 39754184, 2025). "Hyperprolactinemia (HPRL) refers to a state in which the level of peripheral blood prolactin (PRL) is continuously increased due to various reasons, and its etiology can be classified into 4 categories: physiologic, pathological, pharmacologic, and idiopathic." (PMID 39792764, 2025). "Hyperprolactinemia (HPRL) refers to a state of persistently elevated prolactin (PRL) levels in peripheral blood." (PMID 40964426, 2025). "Our study demonstrates a significant relationship between hyperprolactinemia and primary infertility, revealing that women with primary infertility have substantially higher prolactin levels compared to those with secondary infertility." (PMID 40535391, 2025). "With the loss of dopaminergic inhibition, lactotroph cells begin to secrete prolactin autonomously, ultimately leading to the development of hyperprolactinemia." (PMID 41480352, 2025). "In a clinical trial, the correction of prolactin levels in male patients with severe hyperprolactinemia using medications such as cabergoline (CAB) or bromocriptine (BRC) improved hypogonadism-related symptoms." (PMID 40966237, 2025). "Hypogonadism, presenting with low libido, erectile dysfunction, and gynecomastia, frequently occurs in men with hyperprolactinemia, typically characterized by elevated serum prolactin, suppressed gonadotropins, and low testosterone." (PMID 40966237, 2025). "Hyperprolactinemia, defined as prolactin levels exceeding the upper normal limit, is considered the most common endocrine disorder of the hypothalamic-pituitary axis and has multifactorial etiology." (PMID 40507082, 2025). "While elevated prolactin generally supports nurturing behaviors and anxiolysis, chronic stress, hyperprolactinemia, or disruptions in prolactin signaling can paradoxically promote anxiety, depressive symptoms, and impaired maternal care." (PMID 40565372, 2025). "One of the studies revealed that in women with polycystic ovary syndrome and hyperprolactinemia who were receiving metformin, the addition of probiotics to metformin therapy significantly reduced prolactin levels compared to metformin therapy alone." (PMID 39940263, 2025). "Thirteen significant signals were identified in women, including weight increased, galactorrhea, elevated blood prolactin, hyperprolactinemia, injection site erythema, and others." (PMID 39833706, 2025). "In the cases of PRL secreting PitNETs, surgery and female gender were independent predictors of control of hyperprolactinemia." (PMID 40276548, 2025).